MTOR (mechanistic target of rapamycin kinase)
Diseases named in the same sentence as MTOR in open-access papers (continued):
Sharing a sentence is not in itself a finding about the gene and the disease.
prostate carcinoma (continued). "Further, it has been suggested that one function of AR in PTEN-deficient prostate cancer cells is to promote the pathologic activation of mTOR, providing a potential mechanistic link between these two pathways in prostate cancer." (PMID 22614157, 2012). "Of note, dysregulation of the PI3K/AKT/mTOR pathway has been implicated in the malignant transformation accompanying prostate cancer progression." (PMID 22614157, 2012). "Current estimates suggest that PI3K/Akt/mTOR signaling is upregulated in 30–50% of prostate cancers, often through loss of PTEN function." (PMID 22454635, 2012). "In this study, we thoroughly captured common genetic variation across 67 genes in the mTOR pathway and to our knowledge, this is the most comprehensive evaluation of common and coding variation in the mTOR pathway genes in relation with prostate cancer risk." (PMID 21373201, 2011). "When the association is then compared with cancers in which the mTOR inhibitor temsirolimus has been used, prostate cancer also gives the strongest correlation as the disease in which this drug has been most commonly used." (PMID 20234771, 2010). "For maintenance therapy after KT, the use of TAC might be the protective factor of prostate cancer [0.92(0.96~1.00)], while CSA and mTOR could increase the risk of prostate cancer [1.24(1.18~1.31)], [1.31(1.24~1.39)]." (PMID 41001029, 2025). "Notably, SP5’s association with the activation of the AKT/mTOR signal pathway in prostate cancer, hints at intriguing regulatory mechanisms governing SERPING1 transcription that warrant further investigation." (PMID 39962118, 2025). "Similarly, the PI3K/AKT/mTOR pathway is a key regulator of cell survival and proliferation, and its dysregulation has been linked to prostate cancer progression and therapy resistance." (PMID 41056440, 2025). "The pathway most affected by MTA1 overexpression in the PTEN-loss prostate was the mTORC1 (hereafter mTOR) pathway, which is known to be aberrantly activated in castration-resistant prostate cancer and advanced prostate cancer with a reduced expression of PTEN." (PMID 38611022, 2024). "Similarly, mTORC1 interacts with AR in prostate cancer cells and androgens reprogram mTOR–chromatin associations in an AR-dependent manner." (PMID 38727317, 2024). "In addition, it was reported that RNF7 exhibits an oncogenic role in the development of prostate cancer interacting with PTEN-loss via activating the PI3K/Akt/mTOR signaling pathway." (PMID 36644576, 2023). "Upregulation of mTOR is strongly associated as a driver of prostate cancer metastasis." (PMID 38628976, 2023). "Downregulation of PI3K/Akt/mTOR signaling pathway proteins occurs subsequent to EpCAM silencing and is associated with the decreased colony formation, proliferation, and cellular invasion in prostatic cancer cells." (PMID 35986321, 2022). "Ultimately, glutamine secretion by CAFs serves as an energy source for prostate cancer cells through anaplerosis causing metabolic reprogramming via elevated mTOR signaling in prostate cancer cells to facilitate CRPC growth and neuroendocrine differentiation of prostate adenocarcinoma." (PMID 36671452, 2022). "Moreover, PI3K/mTOR pathway is indicated as one of the main causes of prostate cancer resistance to therapy." (PMID 34832087, 2021). "In conclusion, the TG genotype of mTOR rs2295080 may be linked to reduced susceptibility to urinary system tumors or specific prostate cancers in Chinese patients." (PMID 32597485, 2020). "In addition, curcumin was found to abrogate cancer associated fibroblast-induced prostate cancer cells invasion by downregulating monoamine oxidase A (MAOA)/mammalian target of rapamycin (mTOR)/hypoxia-inducible factor-1α (HIF-1α) signaling pathway." (PMID 31547193, 2019). "This was further supported by inhibiting IKK activity in PTEN-deficient prostate cancer cells by the mTOR inhibitor rapamycin through a mechanism that may involve dissociation of Raptor from mTOR." (PMID 31284467, 2019).
prostate carcinoma (continued). "In Tripathi’s research, POTEE could interact with mTOR and Rictor (Rapamycin-insensitive companion of mTOR) proteins in tumor associated macrophages of prostate cancer, and then enhanced cell growth and proliferation through immune modulation." (PMID 31723122, 2019). "Similarly, in kidney and prostate cancer cells, resistance towards the mTOR-inhibitor everolimus has been associated with increased mitotic activity." (PMID 31167517, 2019). "Developing combination therapy for castrate-resistant prostate cancer (CRPC) may require exploiting new drug targets outside androgen receptor and PI3K / AKT / mTOR signal transduction pathways implicated in prostate cancer (PCa) progression." (PMID 30382885, 2018). "Finally, miR-100 was also shown to be significantly downregulated in our data; this was a miRNA of interest as it has been implicated in prostate cancer as a repressor of the oncogene mTOR." (PMID 30349559, 2018). "MTOR c.1437T>C was reported to be linked to the MTOR rs2295080 (c.-141C>A), a promoter variant, of which GT genotype was previously associated with less risk for prostate cancer." (PMID 30487748, 2018). "PI3K/AKT and the downstream mTOR/S6 kinase were reported important for activating the translation of PD-L1 protein in variant types of cancers, including non-small cell lung cancer, prostate cancer, glioma, as well as in TNBC." (PMID 28465490, 2017). "Notably, these genes were involved in many KEGG pathways that are associated with cancer, such as endometrial cancer, prostate cancer, colorectal cancer, non-small cell lung cancer, and the mTOR signaling pathway." (PMID 26831400, 2016). "To study whether G6PD was regulated by mTOR signaling in vivo, we performed immunohistochemical analysis of two different autochthonous in vivo models of prostate cancer caused by Pten loss-of-function." (PMID 24861463, 2014). "SNPs in the PTEN/AKT/mTOR axis associated with the prostate cancer risk." (PMID 22815832, 2012). "Activation of AMPK by B-DIM resulted in the down-regulation of AR and prostate-specific antigen (PSA) expression, and caused induction of cell apoptosis, suppression of mTOR pathway, and inhibition of prostasphere formation in human prostate cancer cells in vitro and in vivo." (PMID 23056607, 2012). "Recently mTOR signaling has been implicated in regulating the translation of factors important for metastasis in prostate cancer suggesting that translational control of adhesion and migration may be a common theme in cancer pathogenesis." (PMID 22693568, 2012). "We hypothesized that genes belonging to the mTOR pathway may be centrally implicated in cancer development, including prostate cancer, and that polymorphic alleles of these genes might affect prostate cancer risk." (PMID 21373201, 2011). "In addition, NPRL2 was found to be significantly upregulated in docetaxel-resistant prostate cancer cells and associated with decreased mTOR signaling and elevated autophagy; depleting NPRL2 in these cells increases sensitivity to docetaxel by inducing apoptosis." (PMID 38915098, 2024). "Moreover, PI3K/Akt/mTOR signaling pathway is associated with prostate cancer radioresistance." (PMID 28064447, 2017). "In addition to AR signaling, the PI3K/Akt/mTOR pathway is associated with prostate cancer." (PMID 26506516, 2015). "However, for studies of androgen, it was believed that androgen might stimulate mTOR activity in PTEN-deficient prostate cancer cells." (PMID 23555892, 2013). "Since the Akt proto-oncogene is an important node in the mTOR signalling network, we may begin by characterising the text-mined associations of different tumor subtypes with Akt; this analysis shows that the strongest association is with prostate cancer." (PMID 20011464, 2009).
prostate carcinoma (continued). "Preclinical studies consistently demonstrate that carbohydrate restriction and KD can slow tumor growth, modulate key oncogenic pathways such as PI3K/AKT/mTOR, reduce systemic insulin signaling, and enhance survival in prostate cancer models." (PMID 42194907, 2026). "Validation experiments included Western blotting, co-immunoprecipitation, and pharmacological inhibition using OGX-427 and mTOR inhibitors (Everolimus, Sapanisertib) in prostate cancer cell lines, patient-derived organoids (PDOs), and xenograft models." (PMID 41877198, 2026). "Afrocyclamin A inhibits the phosphorylation of PI3K, Akt, and mTOR in prostate cancer DU-145 cells, induces autophagic vacuole formation, and suppresses cancer cell migration and invasion in a dose-dependent manner." (PMID 41227351, 2025). "A Phase II study (NCT00976755) of everolimus, an mTOR inhibitor, was conducted in patients with metastatic castration-resistant prostate cancer." (PMID 41216191, 2025). "Several inhibitors (rapamycin analogs) targeting the PI3K/AKT/mTOR pathway have been investigated to counteract the mechanism by which PTEN deletion promotes prostate cancer progression, but their antitumor effects have been disappointing." (PMID 39917165, 2025). "TET2 inhibition and decreased 5hmC levels activate key prostate cancer‐related pathways, including the mechanistic target of rapamycin kinase (mTOR) and AR pathways, which drive prostate cancer development." (PMID 40599235, 2025). "Our findings revealed that silencing the NCAPH gene effectively suppressed proliferation, reduced cell cycle progression in prostate cancer cells by directly inhibiting the PI3K/AKT/mTOR pathway, and decreased the expression of the transcription factor E2F1." (PMID 39991770, 2025). "have found that combination of rapamycin and bicalutamide (anti-androgenic drug) improved anti-prostate cancer effect due to the suppression of mTOR stimulated AR transcriptional activity." (PMID 39917165, 2025). "Signaling pathways related to cancer and cell apoptosis, such as the mTOR pathway, the FoxO signaling pathway, apoptosis, the prostate cancer signaling pathway, and the MAPK pathway, were significantly enriched." (PMID 40507874, 2025). "Studies have shown that Elesclomol–Cu in prostate cancer can enhance cellular response to docetaxel by activating copper accumulation dependent on the DLAT/mTOR pathway (which occurs both in vitro and in vivo)." (PMID 41463095, 2025). "The knockdown of CD44v6 in prostate cancer cell lines has been demonstrated to enhance chemo/radiosensitivity, with the underlying mechanism involving the downregulation of the PI3K/AKT/mTOR and Wnt/β-catenin signalling pathways." (PMID 41168417, 2025). "Studies have shown that the dual PI3K/mTOR inhibitor NVP-BEZ235 significantly reduces the survival rate of prostate cancer PC-3 cells post-radiation." (PMID 40725100, 2025). "Collectively, the data suggests that the interaction between SMC4 and GLUT1, as confirmed by co‐IP, promotes prostate cancer cell metastasis through the Rheb/mTOR pathway." (PMID 40278414, 2025). "Elevated phosphorylated AMPK levels and decreased phosphorylated mTOR levels induce autophagy in prostate cancer cells." (PMID 40661871, 2025). "In a study on the PTEN deleted mouse model of prostate cancer, a blockade of mTOR inhibited prostate tumorigenesis in epithelial cells." (PMID 39917165, 2025). "While further research is necessary, our findings suggest that SESN2 has potential anticancer effects in prostate cancer by modulating AMPK/mTOR-mediated autophagy." (PMID 40661871, 2025). "In PTEN-deficient prostate cancer mouse models, SAG deletion suppresses the abnormal activation of PI3K/AKT/mTOR signaling." (PMID 41343534, 2025).
prostate carcinoma (continued). "They found that prominent CE accumulation, which only occurred in advanced prostate cancer, is a consequence of the loss of tumour suppressor PTEN and subsequent activation of the PI3K/AKT/mTOR pathway." (PMID 40723223, 2025). "At the molecular level, succinylation of a specific protein, for example, CPT1A, causes succinylation of SP5 at K391, which activates the master signaling pathway PDPK1-AKT/mTOR and promotes proliferation and survival of prostate cancer cells." (PMID 40865948, 2025). "In breast and thyroid cancer, overexpressed miR-222-3p induces proliferation, migration, and invasion, while in castration-resistant prostate cancer, exosomal miR-222-3p upregulates such malignant behaviors by activating mTOR signaling." (PMID 41516091, 2025). "Although mTOR inhibitors are effective in many cancers, they have shown limited efficacy in the treatment of prostate cancer." (PMID 38611022, 2024). "Activation of the P13K/Akt/mTOR pathway has been reported to occur in approximately half of advanced prostate carcinoma with significant cross-talk between P13K/Akt/mTOR and AR signaling." (PMID 39273701, 2024). "Prostate cancer (PCa) cells rely on androgen receptor (AR) signaling, and therapies targeting this pathway can inadvertently activate compensatory mechanisms like mTOR." (PMID 39796704, 2024). "Taken together, OTUD7B promotes the proliferation, and autophagy, and inhibits apoptosis of prostate cancer cells via the AKT/mTOR signaling pathway." (PMID 38935308, 2024). "The manuscript discusses how lncRNAs like HULC and RHPN1-AS1 influence autophagy and therapy resistance in prostate cancer by interacting with pathways like mTOR and EGFR signaling." (PMID 39512820, 2024). "Verbascoside inhibits TGF-β and the EMT process through the HMGB1/RAGE axis, thereby reducing cell proliferation and invasiveness in prostate cancer via the PI3K/AKT/mTOR pathway." (PMID 38529373, 2024). "Two genes (SYNPO2, PCYT1A) act in the Pi3K/Akt/mTOR pathway, involved in carcinogenesis of many tumours including colorectal-, gastric- and prostate cancer." (PMID 39543761, 2024). "For instance, TM9SF4 induces autophagy by suppressing mTOR phosphorylation, thereby enhancing anoikis resistance and metastatic potential in prostate cancer cells." (PMID 38460046, 2024). "ChIP-sequencing datasets revealed that mTOR directly binds to thousands of regulatory regions of polymerase II-transcribed genes in both mouse liver and human prostate cancer cells." (PMID 39349819, 2024). "Among the analyzed SNPs, the mechanistic target of rapamycin kinase (MTOR) rs17036508, MTOR rs2295080, regulatory associated protein of MTOR complex 1 (RPTOR) rs1468033, and AKT2 rs7250897 are associated with prostate cancer risk in Chinese men." (PMID 38287309, 2024). "When Piezo1 is activated, calcium flow can be increased to further activate the Akt/mTOR signaling pathway, leading to Akt/mTOR phosphorylation, which promotes the proliferation and migration of prostate cancer cells and the growth of prostate tumors." (PMID 38690080, 2024). "It has been shown that inhibitors of Akt and mTOR significantly reduce proliferation of prostate cancer cells." (PMID 38732504, 2024). "Patients in the LSG group were more sensitive to CZC24832 and Erlotinib AZD2014 has shown antitumour effects as an mTOR inhibitor in a variety of cancers including prostate cancer and HCC." (PMID 39663596, 2024). "We report here that gnetin C effectively suppressed the MTA1/mTOR pathway indicated by the downregulated MTA1 and the associated reduced phosphorylation of AKT, mTOR, S6K, 4EBP1, and CyclinD1 in PC3M prostate cancer cells." (PMID 38611022, 2024). "MiRNAs − 410-3p has been shown to have oncogenic activities in prostate cancer through the PTEN/AKT/mTOR pathway." (PMID 38965615, 2024). "Androgen receptor signalling reportedly promotes the PPP through mTOR-mediated up-regulation of G6PD in prostate cancer." (PMID 39025830, 2024).
prostate carcinoma (continued). "Our study is the first to show a decrease in phosphorylation/activation of mTOR and p70 S6K with CA treatment in PC-3 prostate cancer cells." (PMID 38732504, 2024). "Increased activation of the PI3K/AKT/mTOR (PAM) pathway is frequent in prostate cancer (PC), often as a resistance mechanism to androgen therapy." (PMID 39092562, 2024). "Our study corroborated these findings, demonstrating that MA induces autophagy in prostate cancer cells via the mTOR signaling pathway." (PMID 39624845, 2024). "Preceding studies showed that α-linolenic acid and other omega-3 fatty acids demonstrated a repressive effect on the PI3K/AKT/mTOR pathway in hepatic steatosis and prostatic cancer." (PMID 39519654, 2024). "Benzalutamide (a new generation of hormonal agents) significantly up-regulates total and phosphorylated levels of Akt and mTOR in prostate cancer cell lines (LNCaP and CWR22RV1 cells)." (PMID 39465848, 2024). "Dysregulation of the PI3K/AKT/mTOR pathway in advanced prostate cancer and its implication in treatment resistance has been reported." (PMID 38225213, 2024). "In conclusion, these data demonstrate that concurrent blockade of the PI3K/AKT/mTOR and AR pathways has superior antitumor efficacy and induces apoptosis in androgen-sensitive prostate cancer cell lines and PDX models." (PMID 38225213, 2024). "A study involving prostate cancer cell lines discovered that compounds aimed at the mTOR pathway were able to inhibit cancer cells in both 2D and 3D cultures, whereas those targeting the AKT pathway showed reduced effectiveness in 2D cultures." (PMID 39770404, 2024). "It has been reported that miR-101-3p targets CUL4B to block the PI3K/AKT/mTOR pathway in prostate cancer cells." (PMID 38532426, 2024). "Currently Akt (MK2206) and mTOR (Temsirolimus) inhibitors are being evaluated in clinical trials for patients with various forms of cancer including prostate cancer (NCT01480154, 00919035)." (PMID 38732504, 2024). "PLK1 can activate the PI3K/AKT/mTOR pathway to elevate SREBP-dependent expression of key lipid biosynthesis enzymes in castration-resistant prostate cancer." (PMID 38649345, 2024). "Inhibitors of the mitochondrial unfolded protein response targeting HSPD1 induced accumulation and metabolic stress of polyubiquitinated proteins, thereby inhibiting AKT/mTOR signaling in prostate cancer." (PMID 39430254, 2024). "Considering the intricacy of the mTOR signaling network in prostate cancer, it is understandable that preclinical studies would also reflect this complexity." (PMID 38611022, 2024). "For example, lncRNA HULC and RHPN1-AS1 have been shown to regulate autophagy and influence therapy resistance in prostate cancer through their interactions with mTOR and EGFR signaling, respectively." (PMID 39512820, 2024). "The activation of PI3K–AKT via p38–MAPK signaling promotes mTOR activation in pre-senescent prostate cancer cells, as well as in senescent cancer cells induced by chemotherapy or radiation treatment, thereby suppressing its negative activity against NF-κB." (PMID 39201363, 2024). "PI3K/AKT/mTOR pathway regulation by ascorbic acid has been also described in prostate cancer and it has been reported that vitamin C is able to induce AKT ubiquitination and degradation in thyroid cancer." (PMID 38425123, 2024). "In this study, to discover a novel natural mTOR pathway inhibitor in prostate cancer, we have established a clinically relevant mouse model to test the efficacy of gnetin C-targeted therapy." (PMID 38611022, 2024).